CTLA4 (cytotoxic T-lymphocyte associated protein 4)
Diseases named in the same sentence as CTLA4 in open-access papers (continued):
Sharing a sentence is not in itself a finding about the gene and the disease.
cancer (continued). "In contrast, EpCAMlow, EpCAM− and full mesenchymal cancer cells downregulated the expression of PD-L1, CD112, and Gal9, and upregulated the expression of CD80 and CD155, ligands of CTLA-4 and TIGIT, respectively." (PMID 38914547, 2024). "Immunotherapies are promising treatments in cancer, aiming to activate the immune system to combat cancer cells, often by blocking immune checkpoint molecules such as PD1, PD-L1, and cytotoxic T lymphocyte antigen 4 (CTLA4)." (PMID 39337337, 2024). "The available ICI drug classes include CTLA-4 inhibitors, PD-1/PD-L1 inhibitors, CTLA-4/PD-1 inhibitor combinations, and CTLA-4/LAG3 inhibitor combinations, with the response to these therapies being highly influenced by the type of cancer." (PMID 38396737, 2024). "In cancer immunotherapy, anti-CTLA-4 antibody inhibits the binding of CD80/CD86 to CTLA-4, therefore binding to CD28 on Treg cells." (PMID 39616333, 2024). "Subsequently, we also explored the correlation between the expression levels of LRP6 and the expression levels of common immune checkpoints in 33 cancers, such as SIGLEC15, IDO1, CD274, HAVCR2, PDCD1, CTLA4, LAG3 and PDCD1LG2." (PMID 38226972, 2024). "Ipilimumab, the antibody against CTLA-4, was the first ICI approved by the FDA in 2011, which is a milestone in cancer immunotherapy." (PMID 38763973, 2024). "If immune modulation is pivotal to cancer therapy in metastatic NSCLC, then we design anti-CTLA4 + anti-PD1/L1 compared with standard chemotherapy." (PMID 38539487, 2024). "Research findings indicated that about half of the cancer individuals experienced positive outcomes from ICIs like ipilimumab (anti-CTLA4) and nivolumab (anti-PD1), which represents a promising advancement in treating cancer." (PMID 38970774, 2024). "In the case of IFN-γ, multiple studies have shown that inhibitors of CTLA-4 and PD-1, as well as other immune checkpoint blockade therapies, increase IFN-γ production, which subsequently results in the elimination of cancer cells." (PMID 39126001, 2024). "Subsequent clinical trials and efficacy assessments resulted in ipilimumab, a CTLA4-targeting monoclonal antibody, receiving approval as the first ICI for cancer treatment 99,100." (PMID 38617537, 2024). "TIGIT, CTLA-4, PD-1, T cell immunoglobulin 3 (Tim3), and lymphocyte activation gene 3 (LAG3) are the most commonly targeted checkpoints for cancer immunotherapy." (PMID 39349422, 2024). "Antibodies targeting PD-1, CTLA-4 and more recently LAG-3 have improved cancer outcomes in many settings." (PMID 39273028, 2024). "Further exploratory analyses revealed that CTLA4, PDCD1, and the cancer antigens MSLN, MUC1, EPCAM, and PROM1 presented significantly increase expression levels in the high-risk subtype group." (PMID 39712016, 2024). "Seventy-four unique Reactome terms were selected in IStoI comparison, including “MAP2K and MAPK activation”, “TRAF6-mediated IRF7 activation”, “CTLA4-inhibitory signaling”, “signaling by Hippo” and “signaling by WNT in cancer”." (PMID 39000404, 2024). "CTLA-4, PD-1, and lymphocyte activation gene 3 (LAG-3) immune checkpoints can be classified as immunotherapeutic targets that impede cancer growth." (PMID 38533510, 2024). "Importantly, if anti-cancer trumps immune activating/modulatory effects, then one would expect that anti-PD1/L1 combined with TKI will be superior to anti-PD1/L1 combined with anti-CTLA4 for the treatment of intermediate-risk RCCcc (if not for poor-risk RCCcc and sRCC)." (PMID 38539487, 2024). "Several inhibitory immunoreceptors, including but not limited to CD28, CD80, CD86, CTLA4, CD276, and CD274, have been identified and studied in cancer in recent decades." (PMID 38831187, 2024). "To assess the potential differences in immunotherapy response between the TAS groups, we used The Cancer Immunome Database (TCIA) to study the effects of PD‐1 and CTLA‐4 treatment." (PMID 38520220, 2024).
cancer (continued). "Lastly, we conducted a pan-cancer analysis, revealing significant correlations between ALPK1 and various immune checkpoints, including PD-L1, CTLA-4, LAG-3, and PDCD1." (PMID 39845963, 2024). "The exhaustion of CD8 + T and NK cells, along with the overexpression of molecular markers such as LAG3, CTLA4, CD274, PD-L1, and HAVCR2, have been identified as key mechanisms by which cancer cells can escape host immunity." (PMID 38956740, 2024). "The combination of anti-PD-1 and anti-CTLA-4 therapy (nivo-ipi) has been officially approved by the US Food and Drug Administration (FDA) for the treatment of a variety of cancers, including colorectal cancer, hepatocellular carcinoma, and other cancers." (PMID 39839773, 2024). "In our study, CD74 expression was found to be increased following cytokine treatment in several cancers, as well as following ICI treatment (anti-PD1, anti-PDL1, and anti-CTLA4), strongly suggesting that CD74 activates the immune response in most cancers." (PMID 38582956, 2024). "Immune checkpoint blockade (ICB) therapies targeting PD1, CTLA4 and LAG3 on CD8+ TIL has proven to be a particularly effective modality of cancer treatment." (PMID 39516648, 2024). "Similar trends were observed in GATA6high carcinoma-infiltrated ROIs, including increased CD27+ activated T cells and decreased CTLA4+ cells (p.adj = 0.003)." (PMID 38733987, 2024). "Persistent exposure to cancer antigens induces CD4 T cell exhaustion by upregulating the expression of several co-inhibitory markers, including PD-1, CTLA-4, TIM-3, and Lag-3, and downregulating the production of cytokines such as IFN-γ18." (PMID 37147330, 2023). "In a recent study, CTLA-4 expression was evaluated in CRC tissues and different cancer cell lines (HT-29, HCT-166, and SW480)." (PMID 36902476, 2023). "Immunotherapies based on antibodies that bind these receptors (CTLA4, PD1) or their natural ligands (PD-L1 for the PD1/PD-L1 pathway) have dramatically improved clinical results for some cancers." (PMID 37122540, 2023). "Immunofluorescence images showed higher expression levels of immunosuppressive markers, such as PD-L1 and CTLA-4, in CD4+ and CD8+ T cells from cancer mucosa of GC patients as the cancer stage increased." (PMID 37153541, 2023). "The novel immunotherapy agents such as inhibitors of PDCD1, TIGHT, IDO1, CD274, CTLA4 and LAG3 were considered had potential survival benefit in several cancers." (PMID 37608927, 2023). "Differentiation clusters, as markers of immune cells, such as CTLA-4, CD25, and PD-1, have been identified as potential immunotherapy targets for malignant tumors in recent years." (PMID 37023088, 2023). "Checkpoint receptors like PD-1/PD-L1 and CTLA-4 can be targeted to prevent CD8+ T lymphocytes from being exhausted and restore their priming, which helps to destroy the cancer cells producing antigens." (PMID 37892995, 2023). "After exploring immune phenomenon scores through The Cancer Immunome Database (TCIA), we found that anti-CTLA-4 immunotherapy was better in the low C5aR1 expression score group." (PMID 36508191, 2023). "In cancer treatment, SMIs may act alone or in combination with approved therapies, namely chemo-, radio-, or immunotherapy, including monoclonal antibodies directed toward PD-1/PD-L1 or CTLA-4, such as nivolumab, pembrolizumab, atezolizumab, or ipilimumab (anti-CTLA-4 mAb)." (PMID 36982802, 2023). "Here, we discuss which types of cancer TIM-3 can serve as a prognostic factor and the influence of coexpressed immune checkpoint inhibitors, such as LAG-3, PD-1, and CTLA-4 on patients' outcomes." (PMID 37567938, 2023). "Immunotherapy using antibodies to target immune checkpoints (immune checkpoint inhibitors, ICIs), including the PD-1/PD-L1 and CTLA-4/CD80 pathways, has shown promising anti-cancer effects in a variety of cancers." (PMID 37234171, 2023).
cancer (continued). "Over recent years, checkpoint inhibitors, such as those targeting CTLA‐4 and PD1 (PDCD1), have been employed as immunotherapy in several cancers." (PMID 37452510, 2023). "The blockage of CTLA-4 with specific monoclonal antibodies allows for the T-cell CD28 protein to bind to CD80-CD86, which activates T-cells, promoting cancer cell lysis." (PMID 37232754, 2023). "Through our pan-cancer analysis, we found that CEP55 was significantly correlated with MDSCs and Th1 cells in most cancers and positively correlated with the expression of checkpoints, such as PD1, CTLA4, LAG3, and TIGIT in certain cancer types." (PMID 37484531, 2023). "Three different ICIs, PD‐1 inhibitors, PD‐L1 inhibitors, and CTLA‐4 inhibitors, have been approved by the U.S. Food and Drug Administration (FDA) for the treatment of various cancer types." (PMID 38062888, 2023). "CTLA-4 can be detected in normal human serum, and higher levels of soluble CTLA-4 in serum have been observed in many types of cancers." (PMID 36593951, 2023). "ICIs, including antibodies targeting anti-CTLA4 and anti-PD-1/PDL-1, have significantly progressed in various clinical trials to treat diverse cancer types." (PMID 37936697, 2023). "Almost all cancers showed a significant relationship between MRPL13 and immune checkpoint suppressor genes, such as VEGFA, CD274 (PD-L1), and CTLA4." (PMID 37827692, 2023). "Over the past decade, immune checkpoint inhibitors such as PD-1/PD-L1, CTLA-4, and LAG-3 have radically transformed management of advanced cancer." (PMID 37583514, 2023). "While all tumors showed CTLA-4 positivity, the intensity of staining varied from weak and/or strong between early (stages I and II) and late stages (stages III and IV) of cancer and within the same stage, demonstrating heterogeneous expression." (PMID 37107632, 2023). "CTLA4 and PD1 are currently the common immune targets in our immunotherapy, and the combination of both blockers has shown good efficacy in cancer immunotherapy." (PMID 37388224, 2023). "In line with this thought, the approval of ipilimumab, a monoclonal antibody against CTLA4, for the treatment of late-stage melanoma in 2011 by the US Food and Drug Administration (FDA) has been the breakthrough in the emergence of cancer immunotherapy." (PMID 37205112, 2023). "We found that PTPN6 expression was positively correlated with PDCD1, CD274, CTLA4, LAG3, HAVCR2, and CD244 in most cancer types in TCGA, including LGG and GBM." (PMID 37737713, 2023). "K-M survival analysis indicated that OS and PFS were better in cancer patients treated with PDCD1, CD274, and CTLA4 with elevated KLRB1 expression." (PMID 37988189, 2023). "Harnessing the immune system to fight cancer has become a reality with the clinical success of immune-checkpoint blockade (ICB) antibodies against PD(L)-1 and CTLA-4." (PMID 36831533, 2023). "Thus, treatment with a single agent may have a negligible suppressive effect on tumors, whereas cotreatment with other immunotherapy methods such as indoleamine 2,3-dioxygenase (IDO) inhibitors or anti-CTLA-4 can have a synergistic effect on cancer treatment and improve patient survival." (PMID 39282109, 2023). "The expression of ICOS mediates infiltration of immune cells and is positive correlated with the expression of PDCD1, CTLA4, and TIGIT in most cancer types." (PMID 36855091, 2023). "Most cancer entities exhibited significantly positive Pearson correlations coefficients, with the highest coefficients for CD4, CD8A, and CTLA4." (PMID 36672341, 2023). "On the other hand, activation of immune checkpoint pathways in the TME, including CTLA-4 and PD1/PDL1, reprograms immune homeostasis and enables cancer cells to evade immune attack." (PMID 37853413, 2023). "Particularly, the employment of CTLA4 and PD1/PD-L1 inhibitors has emerged as an important landmark in cancer immunotherapy." (PMID 37091809, 2023).
cancer (continued). "As a potential therapeutic target for cancer immunotherapy, BTLA is similar to PD-1 and CTLA-4, but possesses different functions." (PMID 36765782, 2023). "Immunotherapy using combined anti-PD-1 and anti-CTLA-4 in the field of NETs has been investigated in two different studies, CA209-538 and DART SWOG 1609, both enrolling patients with metastatic rare cancers." (PMID 37626955, 2023). "Further analyzing transcriptomic data exhibited significantly positive Pearson correlation coefficients for most cancer entities between CXCR4 and the T cell co-receptors CD4 and CD8A, as well as IRF1 and CTLA4." (PMID 36672341, 2023). "Co-inhibitory immune checkpoints, such as PD1, CD47, CTLA4 and LAG3, are highly expressed on T cell in a variety type of cancers, leading to attenuated T cell responses and ultimately immune evasion of cancer cells." (PMID 38035111, 2023). "Up to date, the most relevant and successful immunotherapy treatments have been aimed at blocking PD-1/PD-L1 and CTLA-4/CD80-86 interaction, thus enabling reactivation of Tc cell activity against cancer cells." (PMID 36672279, 2023). "mAbs targeting CTLA4, PDCD1, CD274, and LAG3 have been approved by the FDA for second- and first-line treatment against cancer, whereas mAbs targeting ICOS and CD40 are under investigation." (PMID 37215135, 2023). "Antibody therapies have been successfully used to treat cancers, such as the anti-PD1/PD-L1/CTLA4 antibody for ICBs." (PMID 36604431, 2023). "NUDCD1 was associated with expression levels of recognized immune checkpoints (anti-CTLA-4) and immune infiltrates (e.g., CD4+ and CD8+ T cells) in some cancers." (PMID 37338527, 2023). "Immune checkpoint blockade (ICB) immunotherapy has garnered extensive interest, as targeting immune checkpoint receptors, such as PD-1, PD-L1, CTLA4, and LAG-3, effectively suppresses immunosuppressive pathways in the TME in many cancer types." (PMID 38201511, 2023). "Several immune checkpoint blockade agents, blocking PDL1 and CTLA4 immune checkpoints, are approved by the FDA as cancer immunotherapies." (PMID 37627119, 2023). "Currently only the CTLA4 and PD1/PDL1 immune checkpoints are therapeutically targeted for the treatment of cancer." (PMID 37435963, 2023). "Along with the well-known PD-1, PD-L1, and CTLA-4, and in addition to SIRPα/CD47, TIM-3 has emerged as a promising target in cancer immunotherapy." (PMID 36829496, 2023). "Just as for PD-1, CTLA-4 and TIM-3, LAG-3 is known as a marker of T cell exhaustion and is found overexpressed in different types of cancers or chronic infections." (PMID 37056774, 2023). "For example, the top 15 hub genes in T cells from all types of cancers included those involved in cell-mediated immunity (GZMB, PRF1 and IFNG) and immune checkpoint signaling pathways (TIGIT and CTLA4)." (PMID 36350625, 2023). "Targeting both the CTLA4 and PD1 pathways appears promising and combined therapies can yield improved clinical outcomes for some cancers." (PMID 37122540, 2023). "ICIs that block CTLA-4 and PD1/PDL1 have demonstrated promising therapeutic efficacy in various human cancers." (PMID 37853413, 2023). "Several ICIs against PD-1, PD-L1, CTLA-4, and LAG3 are FDA-approved therapies for several different types of cancers including melanoma, lung, gastrointestinal, breast, and renal cell cancer." (PMID 37274739, 2023). "The results illustrated that CTLA4 and ICOS were negatively correlated with DDR1 among 19 cancers while positively correlated with DDR1 in LAML and LIHC." (PMID 37031216, 2023). "It is conceivable that the fusion WT NVs platform can be extended to concurrently targeting to other checkpoints for synergetic cancer immunotherapy except PD‐1/PD‐L1 and SIRPα/CD47, such as CTLA‐4, LAG‐3, TIGIT and so on." (PMID 37974395, 2023).
cancer (continued). "Overall, receiving simultaneous immunotherapies leads to higher rates of irAEs than monotherapy, and anti-CTLA-4 tend to have more frequent and severe irAEs because CTLA-4 interaction is less specific to T cells and cancer cells than anti-PD-1/anti-PD-L1." (PMID 37661259, 2023). "It was discovered that DCLRE1B expression had a positive link to ICP genes in many types of cancer, especially in PAAD, in which the correlation coefficients of DCLRE1B with PD-1, PD-L1, PD-L2, and CTLA4 were 0.358, 0.577, 0.593 and 0.378, respectively." (PMID 37936074, 2023). "Concerning cancer immunotherapy, CT26 colon cancer cells are sensitive to ICIs, such as anti-CTLA-4 and anti-PD-1 antibodies." (PMID 36798830, 2023). "We analyzed the expression profile of COMMD2 gene and ICGs (CD274, CTLA4, HAVCR2, LAG3, PDCD1, PDCD1LG2, SIGLEC15, and TIGIT) at a pan‐cancer level." (PMID 36205192, 2023). "Immune checkpoints, such as CTLA-4, PD-1, and TIM-3, play important roles in regulating T-cell responses and have been shown to be effective targets for cancer therapy." (PMID 37629087, 2023). "Studies of TCR, and BCR profiles in multiple cancer types have shown that TCR and BCR profiles can be used as predictive biomarkers of response to treatment with CTLA-4 or PD-1 inhibitors." (PMID 36814910, 2023). "In cancer, Tregs mediate the dysfunction of the CD8+ T cells, which is characterized by upregulation of surface inhibitory receptors (e.g., CTLA-4)." (PMID 36845142, 2023). "Several checkpoint proteins, such as CTLA-4, PD-1, TIM-3 and LAG-3, have been identified as regulatory molecules suppressing an effective patient-inherent immune defense of cancer, mainly by T cells." (PMID 37174080, 2023). "We investigated correlations of immunosuppressive markers (e.g., PD-L1, CTLA-4, and IL-10) in CD4+ and CD8+ T cells from cancer mucosa of GC patients." (PMID 37153541, 2023). "Since immune checkpoint inhibitors (ICIs) have been a prominent topic in cancer treatment, the expression of eight ICIs (LAG3, HAVCR2, CD27, TNFRSF14, CTLA4, TMIGD2, TIGIT, and PDCD1LG2) were analyzed between groups in the study." (PMID 37405988, 2023). "In NSCLC, higher levels of TGF-β were associated with an increased expression of inhibitory molecules such as CTLA-4 and TIM3 on cancer cells." (PMID 35634292, 2022). "In cancer research, these platforms enable characterization of immune cell phenotypes and expression of potential therapeutic targets, such as PDL-1 and CTLA-4." (PMID 35454766, 2022). "Cancer immunotherapy involving the suppression of critical Treg-specific proteins like CD25 and the blockade of immune-checkpoint molecules like CTLA4 and PD1 has demonstrated great clinical results in a variety of cancers." (PMID 35222362, 2022). "The combination of CTLA-4 antibody and PFK158 can significantly enhance the inhibition of cancer growth, showing a bright future for immunotherapy combined with targeted glucose metabolism therapy." (PMID 36230492, 2022). "Indeed, monoclonal antibodies that bind to PD-L1, PD-1, or CTLA-4, known as immune checkpoint inhibitors (ICIs), are now being used for the treatment of multiple different human malignancies, which ultimately turn on the patient’s immune system to target their specific type of cancer." (PMID 35632572, 2022). "The key immune checkpoints (CD274, CTLA-4, HAVCR2, LAG3, PDCD1, PDCD1LG2, SIGLEC15, and TIGIT) also had a significant relationship with DTYMK expression in approximately 20 kinds of cancers, except in MESO, PCPG, and UCS." (PMID 36094557, 2022). "Correlation analysis of FDX1 with checkpoint gene expression found a high correlation (p < 0.05) with tumor necrosis factor (TNF)–related immune genes (TNFRSF14, 15, 25) and CTLA4, PDCD1, CD274, NRP1, and VTCN1 in some kinds of cancers." (PMID 36061184, 2022). "The non-linear HR analysis was conducted using the Morris’s cohort of 1,662 patients with cancer, who had received ICB treatment through the blockades of PD1, PD-L1, and CTLA4." (PMID 35720282, 2022).